SCARB2 (scavenger receptor class B member 2)
Diseases named in the same sentence as SCARB2 in open-access papers (continued):
Sharing a sentence is not in itself a finding about the gene and the disease.
myoclonic epilepsy (4 papers, 2011 to 2025). A group of epilepsy syndromes in which myoclonic seizures are a prominent feature. "A previous study implicated variants in the SCARB2 gene in type 3 GD complicated by myoclonic epilepsy." (PMID 41282474, 2025). "The heterogeneous pathology in the kidney and brain suggests that SCARB2/Limp2 has pleiotropic effects that may be relevant to understanding the pathogenesis of other forms of glomerulosclerosis or collapse and myoclonic epilepsies." (PMID 21904677, 2011).
rhabdomyosarcoma (4 papers, 2010 to 2024). A rare aggressive malignant mesenchymal neoplasm arising from skeletal muscle. "Contemporaneously with our work, another EV-A71 receptor—the scavenger receptor class B member 2 (SCARB2)—was identified from rhabdomyosarcoma (RD) cells commonly used for EV-A71 isolation." (PMID 38359079, 2024). "In this study, we used a lentivirus packaging vector to transduce the SCARB2 gene into human embryonic kidney cells, human rhabdomyosarcoma cells (RD) and African green monkey kidney cells (Vero) to create stable expression lines." (PMID 23919614, 2013). "Among them, two transmembrane protein receptors have been investigated in detail and shown to be critical for infection: P-selectin glycoprotein ligand-1 (PSGL-1) in lymphocytes (Jurkat cells), and scavenger receptor class B member 2 (SCARB2) in rhabdomyosarcoma (RD) cells." (PMID 38359079, 2024). "Scavenger receptor class B, member 2 (SCARB2), originally identified as an EV71 receptor on rhabdomyosarcoma (RD) cells, is expressed on a broad variety of cell types." (PMID 23935488, 2013).
COVID-19 (3 papers, 2021 to 2024). A disease caused by infection with severe acute respiratory syndrome coronavirus 2. "Correlation analysis identified SCARB2 is most correlated with tau and GFAP, and EDA2R is most correlated with Nfl, suggesting that these novel proteins are associated with COVID-19-related early or later CNS injury, respectively." (PMID 33737684, 2021). "Finally, SCARB2 and EDA2R proteins correlated with neuronal injury markers, advising above all for the involvement of neuronal impairment in COVID-19." (PMID 35269564, 2022).
deafness (3 papers, 2017 to 2022). An inherited or acquired condition characterized by the complete loss of the ability to hear from one or both ears. "Scarb2-deficient mice, which lack C-terminal of SCARB2, are characterized by the development of deafness, a unilateral or bilateral hydronephrosis, proteinuria, and a peripheral demyelinating neuropathy." (PMID 35955761, 2022). "Our analysis discovered pathogenic heterozygous mutation in another deafness associated gene, SCARB2 (MIM #602257), in both siblings and mother." (PMID 28222800, 2017). "In this case study, we postulated that a combination of SLC26A4, GJB2 and SCARB2 heterozygous mutations may be implicated in deafness, whilst DUOX2 compound heterozygous mutations may be contributed towards thyroid dysfunction." (PMID 28222800, 2017). "In summary, we proposed that PDS in this family could be a polygenic disorder which possibly arises from a combination of heterozygous mutations in SLC26A4, GJB2 and SCARB2 which associated with deafness, as well as compound heterozygous DUOX2 mutations which associated with thyroid dysfunction." (PMID 28222800, 2017).
epilepsy (3 papers, 2011 to 2024). A brain disorder characterized by episodes of abnormally increased neuronal discharge resulting in transient episodes of sensory or motor neurological dysfunction, or psychic dysfunction.
glomerulosclerosis (3 papers, 2011 to 2021). A hardening of the kidney glomerulus caused by scarring of the blood vessels. "Studies have shown that the lack of SCARB2, which may be related to glomerulosclerosis, can also lead to proteolysis failure resulting in tubular proteinuria." (PMID 34512318, 2021).
hepatocellular carcinoma (3 papers, 2019 to 2024). A malignant tumor that arises from hepatocytes. "SCARB2-expressing hepatocellular carcinoma cells or ICAM-1-positive triple-negative breast cancer cells could be targeted by EV71 or Coxsackievirus A, while PVR-expressing glioblastomas could be targeted by polioviruses." (PMID 39335111, 2024).
neuropathies (3 papers, 2018 to 2024). "While EV-A71 has been shown to utilise many different receptors for facilitated cell entry, the scavenger receptor class B2 (SCARB2) protein has been most widely implicated in facilitating EV-A71 neuropathies." (PMID 29386095, 2018). "Patients with SCARB2 mutations have a severe reduction in their vitamin E levels and cannot absorb dietary vitamin E. Finally, inhibiting FXR or supplementing vitamin E ameliorates the neuromotor impairment and neuropathy in Scarb2 knockout mice." (PMID 38635907, 2024).
Obesity (3 papers, 2021 to 2025). Accumulation of substantial excess body fat. "The final nominally significant variant in our results, rs17001654, is an intron variant in SCARB2 with little known clinical significance other than its association with obesity." (PMID 34205853, 2021). "Given that perilipin content in adipocytes from obese individuals is typically low, the increase in PLIN2 observed in SCARB2 knockdown cells suggests that SCARB2 knockdown could potentially mitigate obesity risk by enhancing lipid droplet regulation and reducing fat accumulation." (PMID 40127054, 2025). "The identification of GNB1 and SCARB2 as potential regulators in human subcutaneous adipocytes underscores their importance in obesity-related processes, such as fat accumulation." (PMID 40127054, 2025). "Our findings highlight the significant roles of GNB1 and SCARB2 in lipid metabolism and adipocyte function, providing insights that could inform therapeutic strategies targeting these regulatory genes in obesity." (PMID 40127054, 2025). "This study integrates proteomic data on adipocyte fat accumulation with GWAS data on obesity to unravel the roles of the identified key candidate genes — G protein subunit beta 1 (GNB1) and scavenger receptor class B member 2 (SCARB2) — involved in fat accumulation." (PMID 40127054, 2025).
breast carcinoma (2 papers, 2022 to 2025). "Previous studies have linked elevated SCARB2 to tumor progression in breast cancer and liver cancer, where it regulates key pathways, such as MYC acetylation and tumor-infiltrating immune cell levels." (PMID 41210942, 2025).
co-infection (2 papers, 2013 to 2017). "Provided these SCARB2-dependent viruses sometimes co-circulate during an epidemic of HFMD, these viruses might have a high potential to undergo an intertypic recombination by co-infection of a SCARB2-expressing cell in vivo." (PMID 23441179, 2013). "The up-regulation of SCARB2 transcription induced by CVA16 may increase the possibility of subsequent infection of CVA16/EV71, resulting in the co-infection with two viruses in a single cell." (PMID 28198671, 2017).
demyelinating polyneuropathy (2 papers, 2011 to 2022). Polyneuropathy that is characterized by demyelination of axons. "Scarb2-/- mice have hydronephrosis, deficiency in glomerular filtration and peripheral demyelinating neuropathy but no epileptic sign." (PMID 22032306, 2011).
encephalomyelitis (2 papers, 2017 to 2018). Inflammation of the brain and the spinal cord. "Furthermore, EV-A71 inoculation in a SCARB2-transgenic mouse induced encephalomyelitis clinically analogous to that observed in humans." (PMID 29386095, 2018).
glioblastoma (2 papers, 2024 to 2025). The most malignant astrocytic tumor (WHO grade IV). "Immunofluorescence and RNAi assays in glioblastoma (GBM) cell lines were conducted to assess SCARB2 localization, expression, and cellular functional roles." (PMID 41210942, 2025). "Further in vitro assays confirmed SCARB2 localization primarily at the cell membrane in glioblastoma cells." (PMID 41210942, 2025).
Hyperglycemia (2 papers, 2019 to 2024). An increased concentration of glucose in the blood. "Conversely, when considering streptozotocin-induced hyperglycemia in the SCARB2 transgenic mice, it became evident that this exacerbated various neurological aspects, including hyperglycemia, hind limb paralysis, viral load, and proinflammatory cytokine levels." (PMID 38773966, 2024). "Thus, it is plausible that hyperglycemia significantly contributes to the heightened neurovirulence of EV71 within the SCARB2 transgenic mouse model." (PMID 38773966, 2024).
kidney damage (2 papers, 2021). "We found that SCARB2 rs6823680_CC is a risk factor of nephrotoxicity, which may be due to the decreased expression of SCARB2 in patients with CC genotype and thus lead to kidney damage." (PMID 34512318, 2021).
liver cancer (2 papers, 2023 to 2025). An epithelial or non-epithelial malignant neoplasm that arises from the liver. "We found that SCARB2 positive liver cancer cells co-expressed these known liver CSC markers." (PMID 37739936, 2023).
neuroblastoma (2 papers, 2021 to 2023). Neuroblastoma (NB) is the most common solid, extracranial childhood tumor. "RG/B5-wt and RG/B5-AR were further titrated in Vero, RD, mouse 3T3 expressing human SCARB2 (3T3-hSCARB2), and human SK-N-SH neuroblastoma cells using 50% tissue culture infective dose (TCID50) assay." (PMID 34468173, 2021).
Niemann-Pick disease type C (2 papers, 2017 to 2022). NPC is a complex lipid storage disease mainly characterized by the accumulation of unesterified cholesterol in the late endosomal/lysosomal compartment. "These were the genes encoding for Galactosidase A (GLA), Scavenger receptor class B member 2 (SCARB2), Niemann-Pick disease, type C1 (NPC1) and the CD164 molecule (CD164)." (PMID 29238336, 2017).
asthma (1 paper, 2013). "Finally, we noted that, of the 12 vitamin D lung developmental genes transcriptomically related to asthma susceptibility, 4 – LAMP1, PIP5K1B, SCARB2, and TXNIP – were significantly differentially expressed upon administration of vitamin D to cells derived from asthmatic children." (PMID 24188128, 2013). "As mentioned, 4 of the developmental genes: LAMP1, PIP5K1B, SCARB2 and TXNIP, were differentially expressed in both asthma and upon stimulation of immortalized B-cells derived from asthmatics, suggesting a possible role of these genes in modulating the immune response in asthma." (PMID 24188128, 2013).
atherosclerosis (1 paper, 2022). A disease characterized by the build-up of fatty material and calcium deposition in the arterial wall resulting in partial or complete occlusion of the arterial lumen. "The EC1 subtype highly expressed Vcam1 and Scarb2 genes in the aortic arch, which were reported to be associated with atherosclerosis." (PMID 35473929, 2022). "This study showed that the EC1 subtype highly expressed Vcam1 and Scarb2 genes in the aortic arch, which are reported to be associated with atherosclerosis." (PMID 35473929, 2022).
brain tumor (1 paper, 2025). "Using the CGGA dataset, we examined SCARB2 expression in 2,000 clinical brain tumor samples from Chinese patient cohorts." (PMID 41210942, 2025).
cardiac hypertrophy (1 paper, 2022). "The expression of Scarb2, also known as Limp-2, has been found to be related to cardiac hypertrophy and heart failure in both rat and human myocardium." (PMID 35055737, 2022).
dementia (1 paper, 2014). Loss of intellectual abilities interfering with an individual's social and occupational functions. "We also show that the association at the APOE locus is similar to the one that occurs in AD, in accordance with previous studies, and that the SNCA and SCARB2 associations are different to the ones reported in PD and possibly PD with dementia." (PMID 24973356, 2014).
demyelinating disease (1 paper, 2011). A broad group of disorders that affect the myelin sheaths that cover the neurons. "In the polyneuropathy sample two individuals with demyelinating disease were found to be carriers of a SCARB2 frameshift mutation (c.666delCCTTA)." (PMID 22032306, 2011).
encephalitis (1 paper, 2015). An acute inflammatory process affecting the brain parenchyma. "SCARB2 was histopathologically identified in a number of CNS and non-CNS tissues, including EV71 antigen-positive neuronal cells in human encephalitis cases, and neuronal cells in EV71-infected SCARB2-transgenic mice." (PMID 26181772, 2015).
enterovirus infections (1 paper, 2013). "Recently we have successfully developed transgenic mice expressing human scavenger receptor class B member 2 (hSCARB2, a receptor of EV71 and CVA16) as an animal model for evaluating the pathogenesis of enterovirus infections." (PMID 23936115, 2013).
glomerular disease (1 paper, 2012). "Recently, although novel SCARB2 mutation has been found in AMRF, the pathophysiologic events leading to glomerular disease in cases with SCARB2 mutations remain unknown." (PMID 22693670, 2012).
Hearing impairment (1 paper, 2017). A decreased magnitude of the sensory perception of sound. "Beyond that, mutational analysis also identified that SCARB2 mutation was associated with hearing impairment." (PMID 28222800, 2017).
Hermansky-Pudlak syndrome (1 paper, 2025). Hermansky-Pudlak syndrome (HSP) is a multi-system disorder characterized by oculocutaneous albinism, bleeding diathesis and, in some cases, neutropenia, pulmonary fibrosis, or granulomatous colitis. "Indeed, human mutations in BLOC1S4 are associated with Hermansky-Pudlak Syndrome, a genetic disorder characterized by defects in lysosome-related organelles, while SCARB2 is necessary for lysosomal membrane integrity." (PMID 40813676, 2025).
Lewy Body Disease (1 paper, 2016). "Two common SNPs in linkage disequilibrium with SCARB2, rs6812193 and rs6825004, have been associated with PD and Lewy Body Disease in genome-wide association studies." (PMID 27110593, 2016).
mouth disease (1 paper, 2023). "Therefore, we conclude that the SCARB2 gene has a protective effect on the course of hand, foot, and mouth disease caused by EV71 infection and that SCARB2 gene mutations can reduce the severity of the disease." (PMID 37078358, 2023).
myoclonus epilepsy (1 paper, 2011). "The phenotypical effect of heterozygous SCARB2 mutations has been discussed before in the case of a patient with myoclonus epilepsy and isolated proteinuria." (PMID 22032306, 2011).
polyneuropathy (1 paper, 2011). A disease or disorder affecting more than one nerve. "Note added in proof: A recent report on a patient with PME and a demyelinating neuropathy affirmed our finding that polyneuropathy belongs to phenotype spectrum of SCARB2 mutation." (PMID 22032306, 2011).
Tremor (1 paper, 2024). An unintentional, oscillating to-and-fro muscle movement about a joint axis. "Consistent with a previous report that Scarb2 knockout led to severe neuromotor impairments, such as tremor and hindlimb clasping, we observed similar neuromotor impairment phenotypes in Scarb2−/− mice from 3 months of age." (PMID 38635907, 2024).
infection (59 papers, 2009 to 2025). The state of being infected such as from the introduction of a foreign agent such as serum, vaccine, antigenic substance or organism. "(C) For sSCARB2 inhibition assay, VP1-145 variants were incubated 1 hr at 37 °C with 1 μg of soluble SCARB2 (sSCARB2) before infection of Vero cells (MOI 0.5)." (PMID 39714930, 2024). "SCARB2 has been considered by many investigators to be the primary EV-A71 receptor, in part based on evidence that it was highly expressed on the surface of RD cells and other susceptible permissive cell lines, and that infection was blocked by anti-SCARB2 Ab." (PMID 38359079, 2024). "NCL and SCARB2 co-precipitate form uninfected cells, and infection with EVA71 increases the amount of NCL associated to SCARB2." (PMID 35503380, 2022). "WARS can sensitize cells that are lowly permissive to infection by EV-A71 such as neurons, and greatly increases the susceptibility to EV-A71 in combination with its primary receptor SCARB2." (PMID 33499355, 2021). "Human SCARB2 expression greatly increased susceptibility to certain EV-A71 strains and allowed for infection of mice beyond the neonatal age and resulted in severe limb paralysis and death." (PMID 33499355, 2021). "We demonstrated that both derivatives are dependent on SCARB2 for effective infection, while their specific tropism is linked to a different ability to bind HS and further correlates with the expression level of this attachment receptor in the tested tissues." (PMID 30075025, 2018). "The human SCARB2 transgenic mice older than 6 weeks of age are susceptible to infection by EV71 clinical isolates and coxsackievirus A16, which use SCARB2 as a receptor after intracranial, intravenous, intraperitoneal, and intra-gastric inoculations." (PMID 24742252, 2014). "However, the infection efficiency facilitated by PSGL-1 is significantly lower compared to that mediated by SCARB2, with cytopathic effects associated with PSGL-1 becoming apparent only several days post-infection." (PMID 40006936, 2025). "In contrast, EV-A71 replication was markedly reduced in the RD-SCARB2-KO clones; in a control experiment, susceptibility to infection was restored to KO cells after transfection with a SCARB2 expression plasmid, eliminating the possibility of off-target effects of CRISPR/Cas9." (PMID 38359079, 2024). "The increased susceptibility was observed upon infection of EV-A71 through multiple inoculation routes, suggesting that SCARB2 could function in diverse tissue types to promote pathogenesis in these mouse models." (PMID 33499355, 2021). "Our results show that polymorphisms in SCARB2, rather than those in PSGL-1, were associated with EV71 susceptibility, which also implicates SCARB2 in a more important role in infection efficiency and illustrates how genetic variation in SCARB2 can affect host susceptibility." (PMID 30395634, 2018). "This might indicate that ANXA2 polymorphisms play a less important role in infection efficiency and host susceptibility than SCARB2 and PSGL-1 polymorphisms." (PMID 30395634, 2018). "Transgenic mice that express the human SCARB2 in their CNS neurons, lung pneumocytes, hepatocytes, and intestinal epithelium (i.e., similar profile to humans) have been shown to be susceptible to infection by EV71 after they are 6 weeks of age." (PMID 29238324, 2017). "Functional studies demonstrated that SCARB2 knockdown and EV-A71 infection markedly reduced GBM cell proliferation and enhanced cell apoptosis rate, suggesting its critical role in facilitating viral entry and subsequent antitumor effects." (PMID 41210942, 2025). "In GBM cells, which expresses high endogenous levels of SCARB2, EV-A71 infection or SCARB2 knockdown significantly reduced the SCARB2 expression levels (p < 0.05, p < 0.01)." (PMID 41210942, 2025). "Scavenger receptor class B member 2 (SCARB2) is essential for EV-A71 infection, but mouse SCARB2 is ineffective in adult mice." (PMID 40642060, 2025).